CD4 (CD4 molecule)
Diseases named in the same sentence as CD4 in open-access papers (continued):
Sharing a sentence is not in itself a finding about the gene and the disease.
malaria (continued). "The gradual reduction in CD4+ T cells and steady CD8+ T cells resulted in decreased CD4+/CD8+ T cell ratios in the SIV-infected animals (S, S + P and P + S), but there were significant increases in the CD4+/CD8+ T cell ratio during the acute phase of malaria in both the P and S + P groups." (PMID 35778766, 2022). "Finally, we sought to determine whether malaria 18S copy numbers for HIV-1 positive newly diagnosed volunteers were correlated with age and hematological parameters including CD4+ T cell counts through the first month of the study." (PMID 36506016, 2022). "A drastic increase in IL-10 producing CD4+ T cells was observed at the early stage as well as at later stage of infection with lethal malaria parasites, while with the non-lethal malaria parasites the frequency of IL-10 producing CD4+T cells was significantly less." (PMID 35109868, 2022). "Thus, whole-parasite blood-stage vaccines, such as WKV, induce strong CD4+ T cell responses against universal epitopes, allowing them to confer species-transcending protection, unlike most subunit malaria vaccines against the polymorphic B cell epitopes." (PMID 33995336, 2021). "CD4+ T cells are not known to directly kill the malaria parasite but can indirectly exert antiparasite activity through the production of key cytokines such as IFN-γ and TNF, which are essential mediators of the parasite-specific adaptive immune response (reviewed in reference 28)." (PMID 34663097, 2021). "However, in malaria patients we found high levels of single-positive PD1+LAG-3− and PD1+TIM-3− as well as high levels of double-positive PD1+LAG-3+ and PD1+TIM-3+ CD8+ and CD4+ T cells." (PMID 32983106, 2020). "However, malaria patients showed a strong upregulation of PD1 on both CD8+ and CD4+ T cells." (PMID 32983106, 2020). "Additionally, a combination of viral-vectored malaria vaccines with RTS, S/AS01 may also improve the overall vaccine efficacy by the generation of protective CD8 and CD4 T cell responses along with the strong anti-CSP antibodies." (PMID 32708179, 2020). "Previous studies showed that CXCR3 expression increases on CD4+ and CD8+ T cells in the spleen during P. berghei ANKA infection suggesting this chemokine receptor may be important in T cell trafficking to the spleen during malaria." (PMID 30915078, 2019). "Participating individuals' CD4 values were analyzed against parasitaemia prior to commencement of antimalarial therapy on day 0 and results showed a negative correlation between CD4 count and malaria parasite densities, but the correlation, however, was statistically insignificant (p > 0.169)." (PMID 31354844, 2019). "Besides a moderate fraction of CD4−CD8− T cells and a minor fraction of CD4+ T cells producing GrzB, we could identify CD8+ T cells as being the main GrzB producing T cell subset in malaria." (PMID 31921176, 2019). "Therefore, the codon-optimized VLP vaccination displayed better protection against malaria by inducing higher levels of CD4+ and CD8+ T cells responses than the non-codon optimized VLP vaccination." (PMID 31796032, 2019). "However, none of these platforms have induced robust CD8+ and CD4+ T cell responses as well as antibody responses sufficient for protection against malaria." (PMID 31275867, 2019). "Malaria specific IgM and IgG1 levels were not correlated with CD4 counts." (PMID 31470903, 2019). "Hence, this study sought to address paucity of data on performance evaluation of standard diagnostic Bioline among HIV-positive patients in relation to various factors such as fever status, CD4+ cell count, ART status, co-trimoxazole prophylaxis and malaria density." (PMID 30568892, 2018). "Increased proportions of CD4+ T cells express CTLA-4, OX40, Glucocorticoid-induced TNFR family related gene (GITR), tumor necrosis factor alpha receptor type II (TNFRII), PD-1, LAG3, T-cell immunoglobulin and mucin-3 (TIM3) and CD69 during P. vivax and P. falciparum malarias." (PMID 30631323, 2018).
malaria (continued). "Recently, Foxp3− IL-10-producing Th1 cells (type 1 regulatory; Tr1), rather than thymus-derived FoxP3+ CD4+ regulatory T (Treg) cells, have also been recognized to play important roles in determining the outcome of protozoan parasitic diseases, including malaria, leishmaniasis and toxoplasmosis." (PMID 30459773, 2018). "Furthermore, combined blockade of PD-L1 and Lymphocyte-activation gene 3 (LAG3) immune inhibitory molecules accelerated clearance of non-lethal P. yoelii blood-stage malaria by improving CD4+ T cell functions and increasing antibody titres." (PMID 30631323, 2018). "For a long time, it was assumed that classical αβ CD4 and CD8 T cells were the primary source of malaria-induced IFN-γ as a result of studies where lymphocyte proliferation and IFN-γ production were measured utilizing techniques that could not differentiate between T cells and NK cells." (PMID 28337195, 2017). "However, the frequency of CD4 cells producing IL10 but not inflammatory cytokines (IFNγ and TNFα) was associated with a decreased risk of clinical malaria once infected." (PMID 29097996, 2017). "Given a recent report that PDL2-signalling can compete against the regulatory effects of PDL1, and indeed, can protect against experimental malaria, we speculate that IFNAR1-signalling in cDC regulates CD4+ T cell activation by favouring PDL1-signalling over protective PDL2 signals." (PMID 27812214, 2016). "Another study randomized Kenyan adults taking ART to continue or stop TS prophylaxis, and found that after 1 year of follow-up, TS did not change morbidity and mortality with the exception of fewer malaria cases in the TS arm, and no changes in CD4 count or ART failure were noted over time." (PMID 27431995, 2016). "Furthermore, the mean CD4+ T cell count was lower in patients coinfected with malaria parasites compared to non-coinfected participants (323.5 vs 517.7)." (PMID 27619013, 2016). "Furthermore, the mean CD4+ T cell count was observed to be lower in participants coinfected with malaria compared to non-coinfected participants (323.5 vs 517.7) (p < 0.001)." (PMID 27619013, 2016). "To determine whether malaria-specific CD4+ T cells are maintained in the absence of continued exposure, we compared the frequency and function of P. falciparum-specific CD4+ T cell responses between historically and continually exposed children." (PMID 27660116, 2016). "An alternative explanation could be that an improvement of CD4 cell quality rather than quantity under ART may be important for malaria containment." (PMID 27417903, 2016). "Unlike in the forested area of Tai, where malaria prevalence is stable all year long, the rainy season, the young age of children under 5 yrs, the deficit in CD4 T-cells among HIV-infected patients and the non-use of antimalarial prevention measures were also factors associated with malaria." (PMID 38601357, 2016). "Lastly, it was not possible to investigate the immune responses to malaria which might have provided insight into why CD4 counts had no apparent effect on malaria incidence." (PMID 27417903, 2016). "Interestingly, isolated PD1+CTLA4+CD4+ T cells acted like antigen-specific Tr1-like cells: they suppressed the P. falciparum-specific and anti-CD3/28-induced proliferation of the CD4+ T cell population from malaria patients." (PMID 27802341, 2016). "The decision of whether to stop or continue CTX prophylaxis for malaria in HIV infected patients who are stable on ART should not be based on a patient’s CD4 cell count alone." (PMID 27417903, 2016). "The decision of whether to stop or continue CTX prophylaxis for malaria in HIV infected individuals who are stable on ART should not be based on CD4 counts alone." (PMID 27417903, 2016).
malaria (continued). "As the blockade of CTLA4 and PD1/PDL1 enhanced the proliferative response of PBMC to P. falciparum in some malaria patients, we used these blocking antibodies to assess whether these coinhibitory receptors participate in the suppressive role of PD1+CTLA4+CD4+ T cells." (PMID 27802341, 2016). "However, there were very few malaria episodes in that trial (34 in total), and the authors did not directly examine the relationship between CD4 count and malaria." (PMID 27417903, 2016). "In keeping with previous reports, we found evidence of significantly impaired CD4+ T cell proliferation in continually exposed children, with levels of P. falciparum-specific CD4+ T cell proliferation in these children indistinguishable from the levels in malaria-naïve children." (PMID 27660116, 2016). "IFN-γ priming might further potentiate these interactions—of note, the increased CD4+ T cell proliferation in response to Plasmodium parasites and parasite antigens indicates that IFN-γ priming enhanced antigen presentation during chronic malaria." (PMID 26509177, 2015). "Hence, CD4+ count observed among khat chewer malaria patients was significantly higher (P<0.05) from non-chewer malaria positive patients." (PMID 26173100, 2015). "Mathematical modeling of a Phase IIb trial in which malaria naïve volunteers were given the RTS,S vaccine formulated in either AS01B or AS02A, suggested that the bulk of protection comes from high levels (100–200 μg/ml) of anti-repeat antibodies, aided by robust CD4+ T cell responses." (PMID 25477870, 2014). "Unfortunately, data on CD4 T cell counts were lacking in all except 11 and eight HIV patients with and without malaria, respectively, who had a median CD4 T cell count of 206 cells/μL (range: 14–632) and CD4 136 cells/μL (range: 10–196), respectively (p = 0.215)." (PMID 24505451, 2014). "Under both conditions iRBC-inducible IL-10 production by CD4+ T cells was restored to similar levels, suggesting that the in vivo conditions during acute febrile malaria shape the functional response of CD4+ T cells in a manner that is independent of the in vivo conditioning of APCs." (PMID 24743880, 2014). "Moreover, the CD4+ T cell activation level, as indicated by the percentage of HLA-DR + CD38 + CD4+ T cells, was shown to be positively correlated with the percentage of annexin V + CD4+ TCM and TEM cells during the malaria phase (P = 0.031, r = 0.44 and P = 0.050, r = 0.404; respectively)." (PMID 25487036, 2014). "Both CD4+ and CD8+ T cells have been demonstrated to play an important role in protective antimalarial immunity in mouse models, and experimental challenge models in humans and mice strongly suggest that malaria-specific T cells contribute to protective immunity." (PMID 24415936, 2014). "Interestingly, despite these differences in cytokine production profiles, the overall frequency of malaria-specific CD4+ T cells (i.e. those producing any cytokine) did not statistically differ between the higher and lower incidence groups (P = 0.13)." (PMID 24415936, 2014). "However, such a model has not been sufficient to reflect fully the complexity of CD4+ T-cell biology observed in human or experimental malaria." (PMID 25628621, 2014). "While the approach based on CD25 chosen in this study may be sufficient to deplete CD4+CD127−/loFOXP3+ T cells, more sophisticated mechanistic studies on malaria-induced Treg cells will require highly purified Treg populations that cannot be achieved with the approach chosen here." (PMID 22585585, 2012). "Our study thus raises the intriguing hypothesis that in the our malaria model, CTLA-4 may be the primary regulatory pathway for CD4+ T cells, thereby indirectly affecting CD8+ T cell responses, whereas PD-1/PD-L1 preferentially and directly fulfils this role for CD8+ T cells." (PMID 22319445, 2012).
malaria (continued). "This article describes two cases of HIV-positive patients, who returned from malaria-endemic areas and presented a parasitaemia > 5% of erythrocytes and clinical signs of severe falciparum malaria, both with > 350 CD4 cell count/μl, absence of chemoprophylaxis and successful response." (PMID 22540214, 2012). "However, vaccination with RTS,S/AS01E did not significantly enhance IFNγ-IL2-TNF+ CD4+ T cell responses above those induced by natural exposure to malaria alone." (PMID 23300801, 2012). "Likewise, in P. yoelii malaria, the absence of CD1d-restricted CD4+ T cells leads to increased parasitaemias in the 4th week of infection but not earlier, while the acquisition of protective immunity is not affected." (PMID 21814579, 2011). "In addition, the presence of other CD4+ T cell epitopes may be essential in order to contribute to the enhancement of the CD8+ T cell response, as observed for Chagas disease or malaria." (PMID 21418577, 2011). "CM CD4+ T cells were depleted following SIV infection among all SIV-infected animals, and the co-infected animals failed to generate a CM CD4+ T cell response to parasitemias as observed among the malaria-only animals except for the longest surviving co-infected animal (DK36)." (PMID 19774084, 2009). "Importantly, our study indicates that HIV infection may impair malaria-specific humoral immune responses early on during the course of infection, since many of the HIV-infected women tested had CD4+ T cell counts greater than 400 cells/μl." (PMID 17535103, 2007). "In mice transferred with OVA-pulsed DCs purified from the spleens of malaria-infected mice, however, OVA-specific CD4+ T cells failed to divide to the same extent, suggesting that DCs exposed to malaria parasites are less capable of inducing effective T-cell responses." (PMID 16611373, 2006). "Weaker effect of HIV-1 on mortality in children <5 y in areas of high malaria transmission specifically, analogous to the comparatively weak effect of HIV-1 on incidence in this group: RR = 1.5 at CD4 >500/μL, RR = 2.0 at CD4 200–499/μL, and RR = 5.0 at CD4 <200/μL." (PMID 16229771, 2005). "However, the high frequency of clinical malaria, especially among unvaccinated malaria-naïve infants suggests that phagocytosis by DCs and first-time activation of CD4+ and CD8+ T cells are not fast or efficient enough to protect against the parasites’ challenge." (PMID 37219610, 2023). "Furthermore, there is insufficient evidence to determine whether or not malaria-induced changes in CD4+ T cell counts or viral loads translate to accelerated HIV disease progression or death in areas of stable malaria transmission." (PMID 36104731, 2022). "Thus, immune response tends to become more towards immuno-suppressive with lethal malaria parasite with higher numbers of CD4+ICOS+Foxp3+regulatory T cells whereas with the non-lethal parasite no significant CD4+ICOS+Foxp3+regulatory T cell population was observed." (PMID 35109868, 2022). "Additionally, the subsets of CD4+ T cells that secrete IL-4 or IL-12 provide help in inducing the CD8+ T cell responses and for optimal CD8+ T cell effector activities, respectively, suggesting a CD4–CD8 cross-talk for the development of anti-malaria protective immunity." (PMID 34376691, 2021). "However, CD4+ TH1 is not the only cellular subset that expresses IFN-γ during malaria." (PMID 32043415, 2020). "However, neither the role of CXCR3 expression on T cells in the spleen during malaria nor the phenotype of the T cells, especially of CD4+ T cells, expressing this chemokine receptor have been investigated in mice infected with P. berghei ANKA or in other rodent malaria models." (PMID 30915078, 2019). "However, malaria and VL are not strongly influenced by these CD4+ T cell subsets, which may explain why a relatively minor effect on disease outcome was found in pre-clinical models of these diseases." (PMID 30459773, 2018).
malaria (continued). "In this study that includes children with eBL, who have been residing in malaria endemic areas, we found that overall CD4+ PD-1 expression was significantly elevated in non-survivors while all eBL patients had higher expression of PD-1 on CD8+ T cells compared to healthy malaria-exposed controls." (PMID 28033393, 2016). "Finally, transwell experiments showed that induction of Foxp3 expression, and specifically the generation of Foxp3hi as opposed to Foxp3int CD4 T cells, can be mediated by soluble parasite components smaller than 20 nm and thus likely distinct from the malaria pigment hemozoin." (PMID 24822053, 2014). "Although, it appears that macrophages may not be activated in natural immune response against malaria, interferon gamma(+) and IL-10(+++) secreting CD4 T cells, cytotoxic CD8 T cells, IgG secreting B cells, and NK cells are up-regulated by interferon alpha/beta in malarial infection." (PMID 24188121, 2013). "In the current study, the activity of double-positive CD4 MFT cells (which were not suppressed by the malaria infection) could have partially compensated for the reduction of triple-positive CD4 MFT cells seen at two weeks after the malaria challenge." (PMID 22205939, 2011). "Although well studied in other infections, the surface markers and functional characteristics of CD4 and CD8 cells have not been examined in detail in the context of EBV and malaria coinfections." (PMID 41285032, 2025). "Although not significant, we observed a reduced frequency of CD4+C25+FoxP3+ expressing Ki-67 and CTLA-4 among patients with a previous malaria exposure." (PMID 40726977, 2025). "However, in our mouse model of subclinical malaria, the absence of mature B cells allowed us to eliminate this immune component, anti-plasmodium antibodies, from the equation, and to investigate the contribution of IL-10-producing CD4+ T cells in the regulation of subclinical malaria." (PMID 40972121, 2025). "In settings with a high burden of malaria or severe bacterial infections, CTX should be continued regardless of CD4 count or clinical stage, which is recommended in the guidelines of the Republic of Congo." (PMID 40158188, 2025). "This study aimed to compare RBC indices and anemia in HIV patients’ co-infected with malaria and those HIV patients without malaria and correlates these with CD4 level." (PMID 35245289, 2022). "In the group of malaria-HIV co-infected, CD4 count with RBC and CD4 count with Hgb and in HIV without malaria CD4 count with MCV, CD4 count with MCH and CD4 count with MCHC were positively correlated." (PMID 35245289, 2022). "It is also likely that the delay of blood stage parasitemia by the RhCMV-based malaria vaccines described here was mediated by CD8+ T cells since post-challenge CD8+ T cell responses, but not CD4+ T cells, correlated with decreased parasitemia." (PMID 30673723, 2019). "The exact mechanisms that lead to protection against malaria have not been fully defined, but both specific CD4+ and CD8+ T cells are thought to play a major role in conferring immunity against malaria." (PMID 32038611, 2019). "In settings where severe bacterial infections and/or malaria are highly prevalent, CPT should be initiated regardless of CD4 cell count or WHO clinical stage." (PMID 30042677, 2018). "The most advanced vaccine against malaria is the RTS,S formulated in AS01, which induces strong and protective antibodies as well as CD4+ T cell responses but fails to induce significant CD8+ T cell responses." (PMID 30469323, 2018). "Only children with uncomplicated malaria, but not children with complicated malaria, showed an increase in the proportion of CD39+, CD69+, and GrzB+ CD4+ T cells." (PMID 29555909, 2018).